LINC01560 (long independently transcribed non-coding RNA 1560)
Synonyms: formerly CXorf24
Gene: Long non-coding RNA gene on chromosome X (47,483,571 to 47,484,823, forward strand). Ensembl gene ENSG00000196741.
Diseases named in the same sentence as LINC01560 in open-access papers:
LINC01560 is named in the same sentence as 1 disease in open-access papers, as found by Europe PMC text mining. Sharing a sentence is not in itself a finding about the gene and the disease. The quoted sentences say what the papers report.
osteosarcoma (1 paper, 2020). A usually aggressive malignant bone-forming mesenchymal neoplasm, predominantly affecting adolescents and young adults. "LINC01560 was reported to be aberrantly expressed in osteosarcoma." (PMID 32522293, 2020).